TRPC4 (transient receptor potential cation channel subfamily C member 4)
Diseases named in the same sentence as TRPC4 in open-access papers (continued):
Sharing a sentence is not in itself a finding about the gene and the disease.
Zika virus infection (2 papers, 2024 to 2025). "Our data suggest that TRPC4 may be a key protein underlying some ZIKV infection-induced neuropathological disorders." (PMID 39009885, 2024). "In addition, the reduced ZIKV infection in the presence of HC-070 was associated with significant downregulation of TRPC4 expression." (PMID 39009885, 2024). "Furthermore, we found that in vivo treatment with a TRPC4 channel blocker or an inhibitor of CaMKII, an upstream protein kinase regulating TRPC4 expression, significantly decreased ZIKV infection-associated seizures and improved the survival of ZIKV-infected neonatal mice." (PMID 39009885, 2024). "Therefore, the increased expression of TRPC4 may be a key step underlying seizure induced by ZIKV infection." (PMID 39009885, 2024). "Our findings presented herein will help in developing novel approaches for preventing ZIKV infection and reveal that the TRPC4 channel is a novel potential target for anti-ZIKV drug discovery efforts." (PMID 39009885, 2024). "Our research demonstrates that ZIKV infection leads to an increase in TRPC4 expression within host cells." (PMID 39009885, 2024). "In this study, we have shown that ZIKV infection increases the host TRPC4 protein expression and that pharmacological inhibition of TRPC4 channels or shRNA-mediated TRPC4 gene knockdown are effective in inhibiting ZIKV replication in host cells." (PMID 39009885, 2024). "In this study, we found that ZIKV infection resulted in an increased host TRPC4 protein expression via the CaMKII–CREB pathway." (PMID 39009885, 2024). "Since ZIKV is quickly cleared in ZIKV-inoculated wild-type adult C57BL/6 mice, we used interferon receptor-deficient adult A129 mice (Ifnar−/− mice) and 1-day-old suckling ICR mice to detect whether ZIKV infection affects the TRPC4 level in the mouse brain." (PMID 39009885, 2024). "Here, we reveal a critical role of TRPC4 during ZIKV infection." (PMID 39009885, 2024). "Additionally, Zika virus infection increases transient receptor potential cation channel subfamily C member 4 (TRPC4) expression through the interaction of the viral structural protein 3 (NS3) with Ca2+/calmodulin-dependent protein kinase II (CaMKII), enhancing calcium influx." (PMID 41359105, 2025). "Thus, ZIKV-NS3-dependent activation of Ca2+/CaMKII and phosphorylation of CREB may account for the increase in TRPC4 transcription in response to ZIKV infection." (PMID 39009885, 2024). "We found that HC-070, a potent TRPC4/5 inhibitor, significantly increased BHK cell survival (from 16.4 ± 0.9% to 88.3 ± 1.9%, P < 0.001) following ZIKV infection with an IC50 value of 4.5 ± 3.0 μM (n = 3)." (PMID 39009885, 2024). "We found that ZIKV infection increases TRPC4 expression in host cells via the interaction between the ZIKV-NS3 protein and CaMKII, enhancing TRPC4-mediated calcium influx." (PMID 39009885, 2024). "We show that inhibition of the host TRPC4 channel or CaMKII impedes ZIKV propagation in human brain organoids and improves survival in a neonatal mouse model of ZIKV infection." (PMID 39009885, 2024).
Alzheimer disease (1 paper, 2018). A progressive, neurodegenerative disease characterized by loss of function and death of nerve cells in several areas of the brain leading to loss of cognitive function such as memory and language. "While the P2Y1 receptor is shown to mediate the astrocytic hyperactivity in Alzheimer’s disease, we have identified TRPC4 as a major contributor to the abnormal calcium homeostasis in RTT astrocytes." (PMID 29595472, 2018).
atherosclerosis (1 paper, 2021). A disease characterized by the build-up of fatty material and calcium deposition in the arterial wall resulting in partial or complete occlusion of the arterial lumen. "We need to further establish atherosclerosis animal models to determine the effect of TRPC4 and TRPC5 on the proliferation of VSMCs and VECs under pathological conditions." (PMID 34899056, 2021).
cervical adenocarcinoma (1 paper, 2022). An adenocarcinoma arising from the cervical epithelium. "TRPC1 and TRPC6 mutations mainly occurred in cervical adenocarcinoma, while TRPC4, TRPV and TRPM were mainly mutated in cervical squamous cell carcinoma, which indicated that TRPs mutations could be one of the causes of cervical cancer." (PMID 36072430, 2022).
Cognitive impairment (1 paper, 2021). Abnormal cognition is characterized by deficits in thinking, reasoning, or remembering. "In our study, we observed that both TRPC4 and 5 decreased in hippocampi of KO mice, which indicated that both channels could contribute to the spatial memory impairment of Cx3cr1CreERIL-10−/− mice, although it is difficult to judge which of these channels contributes to cognitive impairment." (PMID 34836549, 2021).
cystitis (1 paper, 2013). Inflammation of the urinary bladder. "Further studies will be necessary to understand the underlying mechanisms by which TRPC1 and TRPC4 promote de novo nerve growth in murine cystitis." (PMID 23922735, 2013). "To assess a possible involvement of TRPC1 and/or TRPC4 in the process of neurite sprouting in cystitis, we compared changes in CYP-treated wild type mice and mice deficient in TRPC1, TRPC4 and TRPC1/C4 (Trpc1−/−, Trpc4−/− and Trpc1/c4−/− mice)." (PMID 23922735, 2013). "Taken together, these results indicate that the CYP-induced cystitis in rats induces the de novo expression of TRPC1 and TRPC4 in bladder sensory neurons." (PMID 23922735, 2013). "Here, we show increased expression of TRPC1 and TRPC4 in bladder-innervating sensory neurons, and provide evidence for their involvement in afferent sprouting and concomitant bladder overactivity in the chronic cyclophosphamide (CYP) model of cystitis." (PMID 23922735, 2013).
diabetes (1 paper, 2020). "The remaining candidate gene, TRPC4, may play a role in diabetes, but the exact mechanism remains obscure." (PMID 32134946, 2020).
focal segmental glomerulosclerosis (1 paper, 2020). A renal disorder characterized by sclerotic lesions in the glomeruli. "Inhibitors of TRPC4/5 are mostly used to target renal diseases such as focal segmental glomerulosclerosis (FSGS), but can also have a therapeutic effect on the central nervous system (CNS)." (PMID 33236980, 2020).
glaucoma (1 paper, 2024). Increased pressure in the eyeball due to obstruction of the outflow of aqueous humor. "Moreover, a few articles have implicated TRPC4 in ocular diseases, including retinitis pigmentosa and glaucoma." (PMID 39108834, 2024). "In glaucoma, the dysregulation of TRPC4 trafficking is thought to contribute to the death of retinal ganglion cells, which leads to optic nerve damage and vision loss." (PMID 39108834, 2024).
Hepatic steatosis (1 paper, 2023). Steatosis is a term used to denote lipid accumulation within hepatocytes. "On the contrary, the use of TRPC4/TRPC5 inhibitors was requested for cosmetic weight loss and treatment of obesity, type II diabetes, MS, and hepatic steatosis (accession numbers: WO/2018/146485; EP3579838; US20200345741)." (PMID 37631015, 2023).
Hypoglycemia (1 paper, 2024). A decreased concentration of glucose in the blood. "We show that insulin-evoked hypoglycemia is severely aggravated in mice lacking the cation channel proteins TRPC1, TRPC4, TRPC5, and TRPC6, which cannot be explained by alterations in glucagon or glucocorticoid action." (PMID 39375537, 2024).
leukaemia (1 paper, 2021). "In this regard, integrated methylome, transcriptome, and epigenetic analysis showed that the expression level of many genes is dysregulated in paediatric leukaemia, and among them, the presence of TRPC1, TRPC4, TRPC3, TRPM2, TRPM4, and TRPM8 also stands out." (PMID 34065398, 2021).
lung squamous cell carcinoma (1 paper, 2013). "In lung squamous cell carcinoma sections, the squamous cells were strongly stained with anti-TRPC1, anti-TRPC3, anti-TRPC4 and anti-TRPC6 antibodies." (PMID 23840757, 2013).
metabolic syndrome (1 paper, 2025). A cluster of metabolic risk factors for CARDIOVASCULAR DISEASES and TYPE 2 DIABETES MELLITUS. "Finally, it would also be interesting to investigate the potential roles of TRPC members in humans, especially the involvement of TRPC4 and TRPC5 in metabolic syndrome." (PMID 40243537, 2025).
multiple myeloma (1 paper, 2022). "The mechanism of action of this novel class of molecules includes the induction of cell death via calcium overload, a finding that was dependent on TRPC1/TRPC4/TRPC5 expression in multiple myeloma cell lines." (PMID 35804837, 2022).
neuropathic pain (1 paper, 2025). Chronic pain caused by damage to nerve fibers. "Further research has found that downregulation of TRPC4 in the TG can reduce neuropathic pain induced by CION and Englerin A. This suggests that TRPC4 contributes to neuropathic pain." (PMID 40202077, 2025).
non-alcoholic steatohepatitis (1 paper, 2022). "Nonetheless, the use of TRPC4/TRPC5 inhibitors for cosmetic weight loss as well as to combat obesity, T2D, MS, NAFLD and non-alcoholic steatohepatitis was recently published (accession numbers: WO/2018/146485; EP3579838; US20200345741)." (PMID 35455971, 2022).
overactive bladder (1 paper, 2013). Symptom of overactive detrusor muscle of the urinary bladder that contracts with abnormally high frequency and urgency. "Our study highlights a crucial role of both TRPC1 and TRPC4 in bladder-afferent nerve sprouting and in bladder dysfunction in a chemically induced overactive bladder model." (PMID 23922735, 2013). "Collectively, our data suggest that TRPC1 and TRPC4 are involved in the sprouting of sensory neurons following bladder cystitis, which leads to overactive bladder disease." (PMID 23922735, 2013). "In conclusion, our data indicated that TRPC1 and TRPC4 are important players in the development of bladder dysfunction in the CYP-induced overactive bladder, by promoting bladder-afferent sprouting in mucosa." (PMID 23922735, 2013).
Pain (1 paper, 2025). An unpleasant sensory and emotional experience associated with actual or potential tissue damage, or described in terms of such damage. "The present work elucidates the significant contribution of TRPC4 in the development of Trigeminal neuropathic pain." (PMID 40202077, 2025).
psoriasis plaques (1 paper, 2011). "Our findings of a diminished TRPC1-, TRPC4- and TRPC6-channel expression were confirmed by immunohistological stainings of punch biopsies from psoriasis plaques." (PMID 21364982, 2011).
retinitis pigmentosa (1 paper, 2024). Retinitis pigmentosa (RP) is an inherited retinal dystrophy leading to progressive loss of the photoreceptors and retinal pigment epithelium and resulting in blindness usually after several decades. "In retinitis pigmentosa, mutations in TRPC4 result in abnormal protein trafficking to the plasma membrane, leading to photoreceptor cell death and vision loss." (PMID 39108834, 2024).
Rett syndrome (1 paper, 2019). A severe neurodevelopmental disorder affecting the central nervous system.
Sepsis (1 paper, 2024). Sepsis is defined as life-threatening organ dysfunction caused by a dysregulated host response to infection. "For instance, TRPC3 blockade has shown promise as a therapeutic intervention in mitigating sepsis development, while the interaction between TRPC5 and TRPC4 contributes to leukocyte accumulation and the release of inflammatory mediators." (PMID 38731999, 2024).
skin cancer (1 paper, 2023). "Taking these considerations and our results into account together, TRPC4 might serve as a potential diagnostic target in skin cancer, but more functional studies are required to fully understand the role of TRPC4 in skin tumor progression." (PMID 36674553, 2023). "We examined the expression profiles of TRPC4 in the most common types of skin cancer." (PMID 36674553, 2023).
skin tumor (1 paper, 2023). "As this is the first study on the expression of the pH-sensitive protein TRPC4 in skin tumors in the literature, our approach is descriptive." (PMID 36674553, 2023). "Even though there is little information on the expression of TRPC4 in skin tumors, the role in cancer progression has been proven in other tissues and it may represent potentially attractive targets for cancer therapeutics." (PMID 36674553, 2023). "Nevertheless, there is no sufficient information about the presence and function of TRPC4 in skin tumors, but all these data suggest that Ca2+ influxes mediated by TRPC4 may contribute significantly to epidermal keratinocyte pathophysiology." (PMID 36674553, 2023).
small cell lung carcinoma (1 paper, 2015). Small cell lung cancer (SCLC) is a highly aggressive malignant neoplasm, accounting for 10-15% of lung cancer cases, characterized byrapid growth, and early metastasis. "In the cell profiling data, the DMS-79 small cell lung cancer cell line was a striking outlier because it was sensitive to englerin A but had low levels of TRPC4 expression." (PMID 26098886, 2015).
Stroke (1 paper, 2020). Sudden impairment of blood flow to a part of the brain due to occlusion or rupture of an artery to the brain. "Since the TRPC4/C5 antagonists inhibit both TRPC4 or TRPC5 homomeric channels and TRPC1/C4 and TRPC1/C5 heteromeric channels, these data support the general idea that targeting TRPC1/C4/C5 channels can be beneficial to stroke therapy including post ischemic protection." (PMID 33490083, 2020).
cancer (25 papers, 2009 to 2023). A tumor composed of atypical neoplastic, often pleomorphic cells that invade other tissues. "Dysregulation of TRPC4 may interrupt Ca2+ homeostasis in cancer cells, which may activate signaling pathways that are highly associated with cancer progression, especially cancer chemoresistance." (PMID 36674553, 2023). "We focus on these proteins because recent studies point to roles in important aspects of cancer: drug resistance, transmission of drug resistance through extracellular vesicles, tumour vascularisation, and evoked cancer cell death by the TRPC4/5 channel activator (−)-englerin A." (PMID 27289383, 2016). "As the expression pattern of NHERF proteins and TRPC4/5 channels is altered in several cancer cell lines and might be linked to cancer progression, the TRPC4/5–NHERF channel complexes should also be reconsidered as potential novel targets for cancer therapeutics." (PMID 30463370, 2018). "We evaluated the distribution of the TRP family in C1–C6 pan-cancer immune subtypes and observed that TRPC4, TRPC6, TRPM4, TRPV2, TRPV4, MCOLN1, and PKD2L1 had the potential to predict the immune subtype." (PMID 36830651, 2023). "A significant correlation was observed between TRPV4/TRPC4 and immune-activation-related genes in almost all 33 types of cancer." (PMID 36830651, 2023). "Given that calcium signaling can impact cell proliferation and migration, some studies suggest TRPC4’s potential role in cancer progression." (PMID 38025430, 2023). "(−)-Englerin A (EA), a potential novel anti-cancer drug, is a potent selective activator of classical transient receptor potential 4 and 5 (TRPC4, TRPC5) channels." (PMID 35165752, 2022). "More recently, studies suggested that its TRPC4/5 activation by EA that inhibits tumour cell proliferation and that EA achieves cancer cell cytotoxicity by inducing sustained Na+ entry through heteromeric TRPC1/TRPC4 channels." (PMID 34203675, 2021). "TRPC4 stimulation in cancer cells induced growth inhibition, which can be blocked by ML204, a TRPC4/C5 inhibitor." (PMID 31801263, 2019). "EA is a remarkably potent activator of ion channels formed by Transient Receptor Potential Canonical 4 and 5 proteins (TRPC4 and TRPC5) and TRPC4 is essential for EA-mediated cancer cell cytotoxicity." (PMID 30038709, 2018). "The data confirm the existence of adverse reaction to EA in mice and suggest that it depends on a combination of TRPC4 and TRPC5 which therefore overlaps partially with TRPC4-dependent cancer cell cytotoxicity." (PMID 30038709, 2018). "The analysis of >500 well characterized cancer cell lines revealed that TRPC4 mRNA abundance is the feature best correlated with sensitivity to (−)EA." (PMID 29865154, 2018). "For example, in tumor cells, the TRPC4/5 channels and the NHERF proteins and NHERF mutations account for cancer progression." (PMID 30463370, 2018). "(−)-Englerin A ((−)-EA) has a rapid and potent cytotoxic effect on several types of cancer cell that is mediated by plasma membrane ion channels containing transient receptor potential canonical 4 (TRPC4) protein." (PMID 27875305, 2017). "We have previously shown that EA-evoked cytotoxicity against cancer cells is explainable by Na+ loading into cells via activation of TRPC4/C14." (PMID 29209034, 2017). "The data suggest that (−)-EA achieves cancer cell cytotoxicity by inducing sustained Na+ entry through heteromeric TRPC1/TRPC4 channels and that the cytotoxic effect of (−)-EA can be potentiated by Na+/K+-ATPase inhibition." (PMID 27875305, 2017). "EA-induced cancer cell-death was in part resistant to a TRPC4 inhibitor ML204 even at high concentrations (>50 μM5,9), suggesting that EA has multiple targets." (PMID 29209034, 2017). "Expression of TRPC4 in cancer cell lines was necessary and sufficient for englerin A mediated growth inhibition." (PMID 26098886, 2015). "TRPC4, TRPV2, TRPV1, and TRPV3 loss variations were found in nearly all cancers." (PMID 35831825, 2022).